CRP (C-reactive protein)
Diseases named in the same sentence as CRP in open-access papers (continued):
Sharing a sentence is not in itself a finding about the gene and the disease.
Neonatal sepsis (continued). "Nevertheless, serum PCT concentration is, based on the literature, more relevant for diagnosing the early stages of neonatal sepsis than serum CRP concentration." (PMID 36834338, 2023). "With advantages of convenience and quickness, CRP has proven to be a good biomarker for neonatal sepsis." (PMID 36357648, 2023). "The discrimination power between suspected and clinical early-onset neonatal sepsis in the postnatal 6th-hour CRP and PCT values was statistically insignificant (CRP; AUC = 0.567, p = 0.259 and PCT; AUC = 0.531, p = 0.599, respectively)." (PMID 37684308, 2023). "More specific, routine testing of C-reactive protein has been shown to have low sensitivity and specificity, and positive predictive value for neonatal sepsis." (PMID 35740783, 2022). "Significant correlations of miR-34a-5p and miR-199a-3p with each of TLC, RDW, RBS, and C-reactive protein (CRP) as well as SNAPII were observed, indicating their associations with the severity of neonatal sepsis." (PMID 34990478, 2022). "Serial CRP monitoring 24 to 48 hours after symptoms has been shown to enhance sensitivity in identifying neonatal sepsis, and serial CRP is also used to assess treatment response in sick neonates on antibiotics for the same." (PMID 35449688, 2022). "C-reactive protein (CRP), procalcitonin, serum amyloid A, and hepcidin are acute-phase proteins that are used to diagnose neonatal sepsis." (PMID 35449688, 2022). "A sliding strip 3D μPAD-based colorimetric assay using antibody-based ELISA was developed for the detection of CRP to diagnose neonatal sepsis." (PMID 35624657, 2022). "Due to the delayed rise of CRP levels as a response to infection CRP has an unacceptable low sensitivity within the first 24 h, i.e., for the early diagnosis of neonatal sepsis." (PMID 35345614, 2022). "The most extensively studied laboratory marker for determining the diagnosis of neonatal sepsis has been CRP." (PMID 35012001, 2022). "Recent meta-analyses documented a good diagnostic value with an overall sensitivity of 62-70% and specificity of 74-89% for CRP in the diagnosis of neonatal sepsis." (PMID 36158418, 2022). "For neonatal sepsis and respiratory infection, there are many biomarkers commonly used in clinical practice: C-reactive protein (CRP), procalcitonin, interleukins, and cell adhesion molecules." (PMID 36140614, 2022). "Clinically, an elevated central–peripheral temperature difference and pulmonary hypertension as well as increased IL-6 and CRP concentrations in blood samples were indicative of neonatal sepsis." (PMID 36233706, 2022). "Laboratory results useful for detecting neonatal sepsis included the concentrations of IL-6 and CRP." (PMID 36233706, 2022). "Antimicrobial peptides LL-37, CRP, and WBC all have early diagnostic value for early onset neonatal sepsis." (PMID 35664882, 2022). "Lin Ruan has published a meta-analysis and a systematic review about biomarker combination in predicting neonatal sepsis, in this study PCT together with CRP improved accuracy of diagnosis of neonatal sepsis ⁠." (PMID 35550043, 2022). "Prediction modelling has reinforced in the pronouncement of several potential biomarkers in the diagnosis of neonatal sepsis which essentially comprehend C-Reactive Protein (CRP), Interleukin-27, neutrophil CD64, etc.." (PMID 34984642, 2022). "Systemic levels of CRP and the ratio of immature to total neutrophils are early indicators of neonatal sepsis." (PMID 35634471, 2022). "Incorporation of laboratory diagnostic markers such as WBC along with standard biomarker such as CRP in the prediction model has considerably reduced the applicability of antibiotics in early-onset neonatal sepsis." (PMID 34984642, 2022). "The acute phase reactant CRP was extensively studied in several contexts, including neonatal lung disease and neonatal sepsis, and it remains the preferred biomarker in many NICUs." (PMID 35669402, 2022).
Neonatal sepsis (continued). "Laboratory results useful for the early detection of neonatal sepsis included interleukin-6 (IL-6) and CRP concentrations." (PMID 36233706, 2022). "The current results demonstrated that miR-34a-5p and miR-199a-3p exhibited significant correlations with each of TLC, RDW, RBS, and CRP, as well as SNAPII, indicating their association with the severity of neonatal sepsis." (PMID 34990478, 2022). "Clinical guidelines in cases of possible early-onset neonatal sepsis require both CRP assessment and positive blood culture." (PMID 34900858, 2021). "CRP, the most frequently used laboratory test for the diagnosis of neonatal sepsis, is extensively studied in routine practice and available as point of care test." (PMID 33407770, 2021). "For other databases, the keywords used include procalcitonin, c-reactive protein, and neonatal sepsis." (PMID 34912626, 2021). "In fact, only the combination of PCT and CRP or presepsin alone improves the accuracy of diagnosis of neonatal sepsis." (PMID 34830040, 2021). "IL-6 has a significant role in the early host response to infection, and its blood level changes precede that of CRP, which makes IL-6 an excellent parameter for the monitoring of neonatal sepsis." (PMID 34708133, 2021). "Various other ratios are being used in the diagnosis of neonatal sepsis, which includes CRP/albumin ratio, neutrophil–lymphocyte ratio, and platelet to lymphocyte ratio." (PMID 34676267, 2021). "Combining CRP with IL-6 was more useful for the early detection of neonatal sepsis compared to each marker alone." (PMID 34708133, 2021). "Serial CRP showed very high predictive values for the diagnosis of neonatal sepsis and was better than those of leucocyte indices of CBC." (PMID 34899922, 2021). "CRP has been proved over the years to have good sensitivity and specificity for the diagnosis of neonatal sepsis." (PMID 33643735, 2021). "Similar observations were reported previously, indicating that CRP evaluation 24–48 h after onset of symptoms has shown to increase its sensitivity for the diagnosis of neonatal sepsis." (PMID 33521320, 2021). "The sensitivity and specificity of eHsp compared with that in CRP test of 11 samples from infants with early-onset neonatal sepsis were 73.3 and 63.2%, respectively." (PMID 34900858, 2021). "Our study also investigates the value of CRP/MPV ratio in diagnosis of late-onset neonatal sepsis in full-term neonates." (PMID 34676267, 2021). "Studies evaluating the role of CRP in the diagnosis of early onset neonatal sepsis (EOS) report varying sensitivity and specificity from 29% to 100% and 60% to 100%, respectively." (PMID 34840718, 2021). "They concluded that CRP can be used for screening of early neonatal sepsis as its sensitivity, specificity, and positive predictive value was high, i.e., 72.2%, 82.1%, and 77.2%, respectively." (PMID 34899922, 2021). "First clinical studies using CRP as biomarker to detect bacterial infections were performed in the late 1980s, and CRP was used in the 1990s for detection of septic neonates showing promising clinical usage of CRP for diagnosis of neonatal sepsis." (PMID 33673378, 2021). "Kaur and Singh studied the role of C-reactive protein and immature to total neutrophil ratio in early-onset neonatal sepsis." (PMID 34899922, 2021). "The sensitivity of NLR (68%) was similar to CRP (78%) for the diagnosis of neonatal sepsis but NLR (46%) had lower specificity as compared to CRP (92%) in this study." (PMID 33643735, 2021). "Whereas CRP is broadly used as diagnostic biomarkers for bacterial infections, PCT is predominantly applied as a diagnostic biomarker in neonatal sepsis." (PMID 34079538, 2021). "For the detection of neonatal sepsis CRP measurement has a sensitivity of 74–98% and a specificity of 71–94% performed at least 12 h after the onset of symptoms." (PMID 33673378, 2021).
Neonatal sepsis (continued). "Panel consensus on CRP was also achieved because its use is in line with a recent introduced national guideline concerning prevention and diagnosis of early onset neonatal sepsis (EONS)." (PMID 33546759, 2021). "Despite the detection of new markers, CRP is still one of the most expressively used acute phase reactants in the diagnosis of neonatal sepsis." (PMID 34676267, 2021). "This manifestation and high levels of serum C-reactive protein (CRP) in three infants are common in neonatal sepsis." (PMID 34188437, 2021). "C-reactive protein (CRP) is an established marker of systemic inflammation and one of the most commonly used and extensively studied markers for the diagnosis of neonatal sepsis." (PMID 34676267, 2021). "This study aims to investigate the optimal cut-off levels and performance of IL-6 and CRP for the diagnosis of neonatal sepsis." (PMID 33233806, 2020). "Receiver operating characteristics (ROC) analyses were done in the assessment of CRP accuracy in diagnosing neonatal sepsis." (PMID 32238170, 2020). "Nonetheless, NLR was still an independent risk factor for neonatal sepsis when PCT and CRP were added to the multivariate regression model." (PMID 33344658, 2020). "In conclusion, C-reactive protein has shown high performance in early diagnosing cases of neonatal sepsis." (PMID 32238170, 2020). "The highest performance of CRP for the diagnosis of neonatal sepsis was observed in the second day measurement with 89.4% sensitivity, 97.3% specificity, 84.5% PPV, and 98.3% NPV." (PMID 33233806, 2020). "The highest performance of CRP for the diagnosis of neonatal sepsis was observed at the second day of serial measurements, CRP2 (8.01 mg/L) with sensitivity (89.4%), specificity (97.3%), PPV (84.5%), and NPV (99.3%)." (PMID 33233806, 2020). "We recommend the combination of IL-6 (≥313.5 pg/mL) and CRP 1 (≥2.15 mg/L) or CRP 2 (≥8.01 mg/L) for early and accurate diagnosis of neonatal sepsis." (PMID 33233806, 2020). "In this study, we attempt to define the optimal cut-off values of serum IL-6 and CRP using ROC curves, and evaluate their performance for early diagnosis of neonatal sepsis." (PMID 33233806, 2020). "Interleukin-6 (IL-6) and C-reactive protein (CRP) are the two most commonly used markers for the diagnosis of neonatal sepsis." (PMID 33233806, 2020). "Recent studies among them have suggested the use of CRP biomarker for the precocious diagnosis of neonatal sepsis." (PMID 32238170, 2020). "CRP levels induced by infection are significantly lower in preterm infants than in term infants, and its sensitivity for the diagnosis of neonatal sepsis is low." (PMID 33081061, 2020). "PCT has satisfactory characteristics as a good marker than IL-6 and CRP for the diagnosis of neonatal sepsis." (PMID 33061986, 2020). "Participating infants in the VB+AB group received intravenous antibiotics for a period of seven days, because of a high suspicion of neonatal sepsis due to overt clinical signs of infection and/or an increased serum level of C-reactive protein." (PMID 32023276, 2020). "This is in agreement with Al-Zahrani and coworkers, who suggested that PCT is more accurate than IL-6 and CRP in neonatal sepsis diagnosis." (PMID 33061986, 2020). "Several biochemical and immunological markers increase in the plasma during neonatal sepsis, such as increased CRP, IL-6, TNF-α, procalcitonin, and E-selectin." (PMID 33233806, 2020). "The combination of IL-6 with CRP 1, CRP 2, CRP3, CRP 4, or CRP 5 showed superior sensitivity with a slight decrease in specificity than the use of IL-6 or CRP alone for the diagnosis of neonatal sepsis." (PMID 33233806, 2020). "Laboratory tests focusing on parameters of neonatal sepsis (blood count and c-reactive protein (CRP)) were obtained within two hours." (PMID 30961665, 2019). "The main finding of this meta-analysis was that presepsin or PCT plus CRP improves the accuracy of diagnosis of neonatal sepsis." (PMID 30463590, 2018).
Neonatal sepsis (continued). "Visfatin concentrations correlated closely with markers of inflammation including C-reactive protein, procalcitonin, interleukin-6 (IL-6), and other cytokines, confirming observations obtained in neonatal sepsis." (PMID 30224938, 2018). "The combination of PCT and CRP or presepsin alone improves the accuracy of the diagnosis of neonatal sepsis." (PMID 30463590, 2018). "CRP is a pentraxin protein which plays an important role in inflammatory and/or infectious stimuli, thus being regarded as acute phase reactant in neonatal sepsis." (PMID 30069260, 2018). "Gestation is significant with neonatal sepsis: premature babies below 33 weeks’ gestation, and low-weight infants are more likely to get infections, and their CRP rises are likely to be less." (PMID 30509228, 2018). "When looking at their explanation for why they chose a CRP < 10mg/L cut-off for an LP, the NICE guideline development group (GDG) based their CRP > 10mg/L recommendation looking at evidence of CRP rises seen in neonatal sepsis." (PMID 30509228, 2018). "CRP is one of the most studied bio markers of neonatal sepsis which is available at most laboratory centers." (PMID 30069260, 2018). "From this study finding, it can be concluded that CRP alone or in combination with WBC count demonstrated a better screening output in neonatal sepsis evaluation for timely management decision." (PMID 30069260, 2018). "The combination of PCT and CRP or presepsin alone improves the accuracy of diagnosis of neonatal sepsis." (PMID 30463590, 2018). "As the CRP level increases in chorioamnionitis or neonatal sepsis conditions, it is used in the obstetrical field to detect infectious conditions." (PMID 28278168, 2017). "To evaluate the association of CRP and inflammatory cytokines in the context of neonatal sepsis, we conducted correlation analysis between CRP and the cytokines TNF-α, IL-6, and IL-10." (PMID 28367457, 2017). "These values demonstrate that CRP cannot be used as a single marker for the diagnosis of neonatal sepsis." (PMID 27689072, 2016). "The sensitivity and specificity of CRP (at 72 hours of admission) in diagnosis of acute neonatal sepsis were 76.92% and 53.49% respectively while it had a positive predictive value of 80% and negative predictive value of 48.94%." (PMID 26150837, 2015). "One of the most commonly used markers for the diagnosis of neonatal sepsis is the C-reactive protein (CRP); however, CRP concentration increases rather slowly in the initial phase of the inflammatory response to pathogens, and its sensitivity is insufficient." (PMID 26380313, 2015). "Scoring system should include other simple to perform and economical tests besides CRP, thus enabling neonatal sepsis early detection." (PMID 26150837, 2015). "In neonatal sepsis, serial CRP measurements have been shown to be helpful in monitoring the response to treatment, to determine the duration of antibiotic therapy, and to recognize possible complications." (PMID 25909192, 2015). "The sensitivity and specificity of CRP in diagnosis of acute neonatal sepsis was 76.92% and 53.49% respectively while it had a positive predictive value of 80% and negative predictive value of 48.94%." (PMID 26150837, 2015). "In most of the time neonates with persistent high CRP levels are more likely to have neonatal sepsis." (PMID 25280754, 2014). "Inflammatory markers such as procalcitonin, C – reactive proteins (CRP) and haematological indices have also been used in diagnosing neonatal sepsis." (PMID 25475836, 2014). "Hematological indices (e.g., numbers of white blood cells, neutrophils, platelets) and biochemical markers of inflammation, such as C-reactive protein, and procalcitonin are routinely used in clinical practice and can aid in the diagnosis of neonatal sepsis." (PMID 23762094, 2013).
Neonatal sepsis (continued). "Cytokines (IL-6, IL-8 and TNF-α), sCD163, and C-reactive protein were serially measured in an attempt to identify a set of tests which can reliably confirm or refute the diagnosis of neonatal sepsis at an early stage." (PMID 23869218, 2013). "Recently, studies have suggested that the diagnostic accuracy of neutrophil CD64 is superior to the IT-ratio and CRP for the early detection of neonatal sepsis." (PMID 24367543, 2013). "CRP is considered a good marker for infection and is found in higher quantity in cases with chorioamnionitis and neonatal sepsis, being more specific for the later stages." (PMID 23401697, 2013). "The present study was therefore carried out to determine the usefulness of C-reactive protein (CRP) for evaluation of neonatal sepsis in Port Harcourt, Nigeria in Sub-Saharan Africa." (PMID 22958461, 2012). "We investigated the impact of routine CRP ordering on clinical decision-making in hospitalized febrile children and neonates with suspected neonatal sepsis, the evidence base for such testing, and the one-year direct medical costs due to this practice." (PMID 22943554, 2012). "Several authors in different settings have reported different performances for usefulness of CRP in the diagnosis and management of neonatal sepsis." (PMID 22958461, 2012). "In this study, we aimed to: investigate the value of PCT and CRP, in establishing the early diagnosis of neonatal sepsis." (PMID 23493845, 2012). "Almost half of CRP tests ordered during the initial workup of neonatal sepsis and about three-quarters of tests performed to investigate or follow-up children with bacterial infections were non-EB." (PMID 22943554, 2012). "Only 12.9% of CRP tests performed on neonates with suspected neonatal sepsis and 29.9% of tests performed on febrile children with suspected bacterial infections informed decision-making." (PMID 22943554, 2012). "In this study, we aimed to investigate the value of procalcitonin, and C- reactive protein in establishing the diagnosis of neonatal sepsis." (PMID 23493845, 2012). "Our results indicated that the sensitivity of procalcitonin (70%) was higher than CRP (45%) for the diagnosis of neonatal sepsis and PCT appears to be a useful marker for the severity of infection." (PMID 23493845, 2012). "Among the clinical features of neonatal sepsis in the present study, CRP performance was highest in neonates with apnoea, vomiting and lethargy and lowest in those with hypothermia and convulsion." (PMID 22958461, 2012). "Kocabas (2007) concluded that PCT and tumor necrosis factor-α are best markers in the diagnosis of neonatal sepsis in comparison with IL-6, IL-8 and CRP." (PMID 23493845, 2012). "Among the numerous biomarkers in the field of neonatal sepsis diagnosis, this review identified 8 predominant markers, as determined by number of publications: CRP, PCT, IL-6, IL-8, IFN-γ, TNF-α, CD64 and sICAM." (PMID 23198119, 2011). "The diagnostic accuracy of serum calprotectin was compared with that of the most commonly used markers of neonatal sepsis (white blood cell count, immature-to-total-neutrophil ratio, platelet count, and C-reactive protein)." (PMID 21765851, 2011). "Although, in recent years, several new markers of infection have beeninvestigated, some studies suggested that CRP remains to be the best diagnostictest for neonatal sepsis." (PMID 19043563, 2008). "In contrast tothese reports, in our study, the order of the markers according to sensitivityand specificity for optimum prediction of neonatal sepsis is CRP >PCT > TNF-α > SAA at the time of diagnosis." (PMID 19043563, 2008). "NET-associated biomarkers do not improve diagnostic accuracy for neonatal sepsis beyond CRP and IL-6." (PMID 42196477, 2026). "As both the sensitivity and specificity of CRP in predicting early-onset neonatal sepsis (EOS) may be low, we aimed to describe CRP levels during the first 36 h of life in term infants born after PROM ≥ 24 h." (PMID 41441318, 2025).